TBX2 (T-box transcription factor 2)
Description:
Transcription factor which acts as a transcriptional repressor. May also function as a transcriptional activator (By similarity). Binds to the palindromic T site 5'-TTCACACCTAGGTGTGAA-3' DNA sequence, or a half-site, which are present in the regulatory region of several genes. Required for cardiac atrioventricular canal formation. May cooperate with NKX2.5 to negatively modulate expression of NPPA/ANF in the atrioventricular canal (By similarity). May play a role as a positive regulator of TGFB2 expression, perhaps acting in concert with GATA4 in the developing outflow tract myocardium (By similarity). Plays a role in limb pattern formation. Acts as a transcriptional repressor of ADAM10 gene expression, perhaps in concert with histone deacetylase HDAC1 as cofactor. Involved in branching morphogenesis in both developing lungs and adult mammary glands, via negative modulation of target genes; acting redundantly with TBX3 (By similarity). Required, together with TBX3, to maintain cell proliferation in the embryonic lung mesenchyme; perhaps acting downstream of SHH, BMP and TGFbeta signaling (By similarity). Involved in modulating early inner ear development, acting independently of, and also redundantly with TBX3, in different subregions of the developing ear (By similarity). Acts as a negative regulator of PML function in cellular senescence. Acts as a negative regulator of expression of CDKN1A/p21, IL33 and CCN4; repression of CDKN1A is enhanced in response to UV-induced stress, perhaps as a result of phosphorylation by p38 MAPK (By similarity). Negatively modulates expression of CDKN2A/p14ARF and CDH1/E-cadherin. Plays a role in induction of the epithelial-mesenchymal transition (EMT). Plays a role in melanocyte proliferation, perhaps via regulation of cyclin CCND1 (By similarity). Involved in melanogenesis, acting via negative modulation of expression of DHICA oxidase/TYRP1 and P protein/OCA2 (By similarity). Involved in regulating retinal pigment epithelium (RPE) cell proliferation, perhaps via negatively modulating transcription of the transcription factor CEBPD.
Synonyms: VETD
Tractability: PROTAC: ubiquitination databases record sites on it.
Gene: Protein-coding gene on chromosome 17 (61,399,630 to 61,409,466, forward strand). Ensembl gene ENSG00000121068.
Subcellular location: Nucleus
Subcellular location (Human Protein Atlas): Nucleoplasm; Cytosol
Pathways (Reactome):
Developmental Biology: Regulation of MITF-M-dependent genes involved in cell cycle and proliferation
Gene Ontology:
Molecular function: DNA-binding transcription repressor activity, RNA polymerase II-specific; protein binding; RNA polymerase II cis-regulatory region sequence-specific DNA binding; sequence-specific DNA binding; sequence-specific double-stranded DNA binding; DNA binding; DNA-binding transcription factor activity, RNA polymerase II-specific; DNA-binding transcription factor activity; DNA-binding transcription factor binding; histone deacetylase binding
Biological process: cardiac jelly development; cellular senescence; endocardial cushion formation; negative regulation of cellular senescence; negative regulation of DNA-templated transcription; negative regulation of transcription by RNA polymerase II; aorta morphogenesis; atrioventricular canal development; atrioventricular canal morphogenesis; cardiac muscle tissue development; cell fate specification; embryonic camera-type eye morphogenesis; embryonic digit morphogenesis; embryonic heart tube development; endocardial cushion morphogenesis; heart looping; muscle cell fate determination; negative regulation of cardiac chamber formation; negative regulation of heart looping; outflow tract morphogenesis; outflow tract septum morphogenesis; pharyngeal system development; positive regulation of cardiac muscle cell proliferation; regulation of heart contraction; regulation of transcription by RNA polymerase II; and 14 more
Cellular component: nucleus; chromatin; nucleoplasm; cytoplasm; transcription regulator complex
Genetic constraint (gnomAD): Loss-of-function variants: 19 observed, 33.5 expected, observed/expected ratio (o/e) 0.57, 90% interval 0.4 to 0.83. The synonymous counts are far from expectation, so gnomAD's model fits this gene poorly and the ratio says little. Missense variants: 992 observed, 846.88 expected, observed/expected ratio (o/e) 1.17, 90% interval 1.11 to 1.23. Synonymous variants: 522 observed, 379.47 expected, observed/expected ratio (o/e) 1.38, 90% interval 1.28 to 1.48.
Homologues: Orthologues: chimpanzee TBX2 (100% identical), macaque TBX2 (99% identical), pig TBX2 (97% identical), dog TBX2 (96% identical), rat Tbx2 (96% identical), mouse Tbx2 (95% identical), guinea pig TBX2 (89% identical), rabbit TBX2 (83% identical), tropical clawed frog tbx2 (72% identical), zebrafish tbx2b (70% identical), zebrafish tbx2a (66% identical), Drosophila melanogaster ocm (23% identical), and 10 more. Paralogues in human: TBX3 (50% identical), MGA (26% identical), TBX1 (24% identical), TBX4 (22% identical), TBX18 (22% identical), TBX5 (22% identical), TBX15 (21% identical), TBX20 (21% identical), TBX6 (21% identical), TBX10 (20% identical), TBR1 (20% identical), TBX22 (20% identical), and 4 more.
Diseases named in the same sentence as TBX2 in open-access papers:
TBX2 is named in the same sentence as 79 diseases in open-access papers, as found by Europe PMC text mining. Sharing a sentence is not in itself a finding about the gene and the disease. The quoted sentences say what the papers report.
breast carcinoma (36 papers, 2006 to 2025). "TBX3 had previously been shown to represses TBX2 expression by directly associating with the TBX2 promoter in a breast cancer cell line, MCF-12A18." (PMID 30979887, 2019). "In breast cancer, TBX2 gene amplification is associated with invasive hereditary BRCA1- and BRCA2-related cancers, high-grade-sporadic breast tumors, and distant metastases." (PMID 22844464, 2012). "Finally, we show that TBX2 and CST6 displayed reciprocal expression in a cohort of primary breast cancers with increased TBX2 expression associating with increased metastases." (PMID 24742492, 2014). "Thus, loss of TBX2 in malignant breast carcinoma cells abolished tumor cell invasion and lead to the restitution of a more differentiated epithelial phenotype." (PMID 22844464, 2012). "Moreover, we found high TBX2 transcript levels to be significantly associated with reduced metastasis-free survival of breast cancer patients, which is in keeping with the correlation of TBX2 gene amplification data with poor clinical outcome." (PMID 22844464, 2012). "The same study showed that reducing TBX2 levels in cisplatin-resistant breast cancer cells led to mitotic catastrophe and drug sensitivity." (PMID 39912718, 2025). "For example, in melanoma and breast cancer, TBX2 functions as a pro-proliferative and anti-senescence factor, and TBX3 promotes migration and invasion." (PMID 39912718, 2025). "Conversely, inhibiting TBX2 in breast cancer, prostate cancer, oesophageal squamous cell carcinoma and lung adenocarcinoma abrogated the expression of mesenchymal markers with reciprocal restoration of the epithelial state." (PMID 39912718, 2025). "For example, in breast cancer and melanoma, TBX2 functions as a powerful pro‐proliferative factor while TBX3 promotes invasion and migration by repressing TBX2." (PMID 40717225, 2025). "Together, these findings highlighted the essential role that the TBX2-CoREST-Sp1 axis plays in maintaining breast cancer survival and revealed its therapeutic potential." (PMID 39912718, 2025). "For example, in breast cancer, two TBX2 complexes have been identified: the TBX2-CoREST complex targets N-Myc Downstream Regulated 1 (NDRG1) by recruiting TBX2 to the NDRG1 promoter via Sp1 transcription factor (SP1)." (PMID 38965548, 2024). "Recent studies indicated that TBX2 was amplified in 8.6%-21.6% of sporadic human breast carcinomas, where the protein was overexpressed." (PMID 38413457, 2024). "Here, we have identified a novel mechanism through which the oncogenic repressor TBX2 interacts with CoREST complex proteins to target growth control and senescence genes, thereby facilitating maintenance of proliferation of breast cancer cells." (PMID 35687133, 2022). "Using the online tool KM Plotter, we see that TBX2 mRNA expression (as evaluated using 4 different probesets) correlated (significantly in most instances) with poor outcomes in ERα breast cancers and within the Triple Negative Breast Cancer (TNBC) subtype." (PMID 35687133, 2022). "As such, the indirect disruption of TBX2 function via targeting specific epigenetic modifiers presents an attractive therapeutic opportunity for the treatment of poor outcome, TBX2-overexpressing breast cancers and other tumour types with TBX2 dependency." (PMID 35687133, 2022). "Genetic or pharmacological targeting of CoREST emulated TBX2 loss, inducing NDRG1 expression and abolishing breast cancer growth in vitro and in vivo." (PMID 35687133, 2022). "The TBX2 gene itself is located on chromosome 17q23, a region which exhibits extensive amplification in breast cancer and neuroblastoma, conferring poor prognosis." (PMID 35687133, 2022).
breast carcinoma (continued). "Nevertheless binding to the Pten promoter, previously reported in muscle, was confirmed, and the reported binding of Tbx2 to the proximal promoter of Ndrg1 in breast cancer cells was also found, although with additional sites occupied within the first intron." (PMID 34819350, 2021). "Early diagnosis biomarkers for breast cancer are mainly concentrated on protein coding genes, such as TBX2/3, Ki-67, HER-2, ER, VEGF and PR, among which HER2 protein expression is acknowledgedly related to metastasis and survival time." (PMID 34057025, 2021). "In contrast, the exogenous expression of cystatin M/E in TBX2-expressing breast cancer cells resulted in upregulated apoptosis." (PMID 33919854, 2021). "Cytotoxicity of these compounds were determined in TBX2-driven breast carcinoma, melanoma, and rhabdomyosarcoma cell lines." (PMID 32195221, 2020). "In breast cancer, it has been shown that the T-box transcription factor family member, TBX2, interacts with EGR1 and this interaction abrogates EGR1 function as a tumor suppressor and downregulates the transcription of the EGR1 gene-dependent program." (PMID 29719592, 2018). "Previous studies have shown that EGR1 interacts with TBX2 in breast cancer and represses the function of EGR1 as tumor suppressor." (PMID 29719592, 2018). "In breast cancer, the interaction of TBX2 with EGR1 represses the putative breast tumor suppressor, NDRG1 (N-myc downregulated gene 1), which is implicated in cell differentiation, apoptosis and senescence." (PMID 29719592, 2018). "TBX2 expression is up-regulated in a wide range of cancers, including melanoma, pancreatic cancer, bladder cancer, breast cancer, colorectal cancer and lung cancer." (PMID 28881763, 2017). "This novel TBX2-CST6-LGMN signaling pathway, therefore, represents an exciting opportunity for the development of novel therapies to target TBX2 driven breast cancers." (PMID 24742492, 2014). "We have previously shown that TBX2 expressing breast cancer cells were addicted to TBX2 and therefore acutely sensitive to TBX2 downregulation, resulting in dramatic growth inhibition and apoptosis." (PMID 24742492, 2014). "In line with previous findings, CGH studies showed that TBX2 appeared to be amplified in approximately 10% of breast cancers." (PMID 24742492, 2014). "We show for the first time that TBX2 mediated transcriptional repression of CST6 is an important event for maintaining the tumorigenesis of a subset of breast cancers, through aberrant activation of the protease LGMN." (PMID 24742492, 2014). "In our initial screen of breast cancer cells we found the OCUB-M cells to be amongst those having an aberrant overexpression of TBX2." (PMID 24742492, 2014). "TBX2 maps to chromosome 17q23.2, a region that is aberrantly amplified in over 40% of breast cancers, 40% of melanomas, 40% of ovarian, 56% of endometrial, and 60% of pancreatic cancers, correlating with poor clinical outcome." (PMID 22844464, 2012). "Overall, these results are compatible with the notion that TBX2 is activated in certain primary breast cancers correlating with an EMT signature and reduced metastasis-free survival." (PMID 22844464, 2012). "A similar tumor subtype distribution of TBX2 overexpression was observed in a panel of a total of 20 human breast carcinoma cell lines using Western blot and qPCR analyses." (PMID 22844464, 2012). "We anticipate our studies to be a starting point for evaluating TBX2 as a new marker for breast cancer diagnosis and potential target for anti-metastatic cancer drug development." (PMID 22844464, 2012). "Taken together, our TBX2 inhibition studies in malignant breast carcinoma cell lines reinforce the notion that TBX2 promotes malignant tumor progression by imparting a highly invasive mesenchymal phenotype on breast epithelial tumor cells." (PMID 22844464, 2012).
breast carcinoma (continued). "Through ectopic expression of TBX2 in normal mammary epithelial cells and RNAi-mediated silencing of endogenous TBX2 overexpression in malignant human breast carcinoma cell lines, we demonstrate that TBX2 acts as a strong cell-autonomous inducer of EMT." (PMID 22844464, 2012). "Yet, studies examining TBX2 expression in a small number of human breast cancers have reported TBX2 mRNA and protein overexpression primarily in the epithelial compartment of tumors with little or no expression in stromal cells." (PMID 22844464, 2012). "Conversely, abrogation of endogenous TBX2 overexpression in the malignant human breast carcinoma cell lines MDA-MB-435 and MDA-MB-157 led to a restitution of epithelial characteristics with reciprocal loss of mesenchymal markers." (PMID 22844464, 2012). "Overexpression of TBX2 in normal breast epithelial cell lines results in reduced expression of E-cadherin and knockdown of TBX2 in breast carcinoma cell lines leads to an increase of E-cadherin expression." (PMID 22844464, 2012). "We note that there was little correlation between TBX2 expression and E-cadherin status in established breast cancer cell lines, a finding, which has also been reported for the EMT-inducing transcription factor LBX1." (PMID 22844464, 2012). "Another dataset showed that TBX2 was higher in poor prognosis metaplastic breast cancers, which like the ‘claudin-low’ group exhibit an EMT gene signature and are highly metastatic." (PMID 22844464, 2012). "TBX2 gene amplification has been detected in primary human breast cancer tumours, pancreatic cancer cell lines, and its overexpression detected in melanoma cell lines." (PMID 17173667, 2006). "Importantly, the knockdown of TBX2 promoted sensitivity to cisplatin in breast cancer and melanoma, to temozolomide in GBM, to carboplatin in ovarian serous carcinoma and to androgen deprivation therapy in advanced prostate cancer." (PMID 39912718, 2025). "Wang and co-workers first demonstrated that TBX2 is a strong inducer of EMT in breast cancer." (PMID 39912718, 2025). "Similarly, ChIP-seq in breast cancer showed that TBX2 interacted with and co-opted numerous transcription factors, leading to tumour suppressor gene repression through recruitment of the CoREST repression complex." (PMID 39912718, 2025). "Indeed, TBX2 confers resistance to temozolomide in glioblastoma, cisplatin in breast cancer and melanoma and platinum‐based chemotherapeutics in ovarian serous carcinoma." (PMID 40717225, 2025). "Together these data suggested that TBX2 may interact with multiple epigenetic regulators and that LSD1 inhibition could represent a viable strategy to target TBX2 dependent breast cancers." (PMID 35687133, 2022). "Interestingly, TBX2 is found in a region of amplification on chromosome 17q23, which is common to about 20% of human breast cancers." (PMID 35846378, 2022). "Because TBX2 is difficult to target, these functional multicomponent complexes, including HP1, could be alternative therapeutic targets for TBX2-expressing breast cancers." (PMID 35159030, 2022). "Similarly, we show in this study that combining LSD1 and HDAC inhibitors produced potent growth inhibition and target gene de-repression in TBX2-expressing breast cancer lines." (PMID 35687133, 2022). "One candidate is TBX2, a key developmental transcription repressor that was identified in a senescence bypass screen in breast cancer, where it was shown to suppress p16INK4A (CDKN2A) expression." (PMID 34819350, 2021). "Data also sustain that the “TBX2-cystatin M/E-legumain” pathway may represent a novel promising axis for the development of innovative therapies to target TBX2-driven breast cancers." (PMID 33919854, 2021). "An increase in TBX2 expression is known to drive breast cancer proliferation and metastasis." (PMID 33919854, 2021).